MIR31HG (MIR31 host gene)
Synonyms: LOC554202; hsa-lnc-31; LncHIFCAR
Gene: Long non-coding RNA gene on chromosome 9 (21,364,605 to 21,591,906, reverse strand). Ensembl gene ENSG00000171889.
Diseases named in the same sentence as MIR31HG in open-access papers:
MIR31HG is named in the same sentence as 53 diseases in open-access papers, as found by Europe PMC text mining. Sharing a sentence is not in itself a finding about the gene and the disease. The quoted sentences say what the papers report.
breast carcinoma (11 papers, 2017 to 2024). "MIR31HG was found to be remarkably upregulated in tumor tissues of esophageal squamous cell carcinoma, pancreatic ductal adenocarcinoma, breast cancer, and basal subtype of bladder cancer, serving as a bona fide diagnostic indicator." (PMID 37950038, 2024). "The expression of lncRNA MIR31HG was upregulated in various types of breast cancers, while MIR31HG was downregulated in triple-negative breast cancer." (PMID 37636269, 2023). "MIR31HG expression was notably upregulated in 20 breast cancer tissues in two cell lines (MDA-MB-231 and MDA-MB435S) collected from BC patients who received surgical resection, contrasting with the former result in 2012." (PMID 37636269, 2023). "Functionally, executed as an oncogene, MIR31HG influences the apoptotic, proliferative, and invasive capabilities, as well as tumour size and clinical stage in breast cancer." (PMID 37636269, 2023). "MIR31HG also exhibited oncogenic properties in breast cancer and esophageal squamous cell carcinoma." (PMID 36060239, 2022). "The contradictory expression patterns of MIR31HG were also found in breast cancer, CRC and gastric cancer." (PMID 32280307, 2020). "Specifically, MIR31HG was found elevated expressed in breast cancer, cervical cancer, chordoma, osteosarcoma, lung cancer, OSCC, PDAC, VSCC and LSCC." (PMID 32280307, 2020). "It has also been shown that MIR31HG is upregulated in breast cancer tissues compared with normal tissues and that higher MIR31HG expression positively correlates with tumor size and staging." (PMID 29165379, 2017). "Lastly, cg05146756 is located close to the promoter of MIR31HG, which regulates proliferation and migration in breast cancer and gastric cancer cells, contributes to hepatocellular carcinoma progression25and is a prognostic predictor for poor outcomes in thyroid cancer26and for malignant cancer." (PMID 39622952, 2024). "We found that in the regulatory network, miR-301a-3p, miR-93-5p, miR-454-3p, miR-181b-5p, XIST, LINC00472, MIR31HG, MEG3, MIR155HG, and LINC00667 have been reported in breast cancer." (PMID 34220926, 2021). "MIR31 host gene (MIR31HG), also named lncRNA LOC554202, was found to be down-regulated in gastric cancer and bladder cancer, but up-regulated in breast cancer." (PMID 28415559, 2017). "In breast cancer and non-small cell lung cancer (NSCLC) cells, MIR31HG expression was upregulated." (PMID 33334367, 2020).
gastric cancer (10 papers, 2017 to 2024). A primary or metastatic malignant neoplasm involving the stomach. "MIR31HG has been associated with unfavorable prognosis in gastric cancer, lung adenocarcinoma, head and neck squamous cell carcinoma, colorectal cancer, and non-small cell lung carcinoma." (PMID 37445988, 2023). "In contrast, MIR31HG was found to be downregulated in gastric cancer hepatocellular carcinoma and esophageal squamous cell carcinoma, and this downregulation was associated with aggressive clinicopathological features and poor prognoses." (PMID 37950038, 2024). "MIR31HG functions as an oncogenic gene in CRC, while LINC01524 is associated with overall survival in gastric cancer with Hp infection." (PMID 39639610, 2024). "On the other hand, in HGC27 cells, MIR31HG inhibited cell proliferation and migration, demonstrating the diverse functions of MIR31HG in different gastric cancer cell lines." (PMID 37636269, 2023). "In contrast, MIR31HG was found to be overexpressed in gastric cancer in Lin’s study, especially in HGC27 and MGC-803 cell lines." (PMID 37636269, 2023). "Recently, the miR-31 host gene (MIR31HG, also known as LOC554202) has been identified in several cancers, such as breast, colorectal, gastric cancer, and pancreatic ductal adenocarcinoma." (PMID 33334367, 2020). "MIR31HG downregulation promotes cell proliferation and was correlated with poor prognosis in gastric cancer." (PMID 27903974, 2017). "In gastric cancer, MIR31HG may suppress cell proliferation and hinder tumorigenesis partly by regulation of E2F1 and p21 expression." (PMID 32280307, 2020). "In gastric cancer tissues and cell lines, MIR31HG was poorly expressed." (PMID 33334367, 2020). "Nevertheless, the expression levels of MIR31HG was reported down-regulated in triple-negative breast cancer (TNBC) cell lines of basal subtype, bladder cancer, gastric cancer, CRC, and HCC." (PMID 32280307, 2020).
pancreatic ductal adenocarcinoma (10 papers, 2017 to 2025). An infiltrating adenocarcinoma that arises from the epithelial cells of the pancreas. "MIR31HG promotes pancreatic ductal adenocarcinoma growth and its downregulation was associated with bladder cancer development." (PMID 27903974, 2017). "In this study, a cancer genomics analysis predicted that MIR31HG overexpression was positively correlated with poorer disease-free survival of pancreatic ductal adenocarcinoma (PDAC) patients, which was associated with upregulation of genes related to TGFβ signaling and the EMT." (PMID 35743003, 2022). "In pancreatic ductal adenocarcinoma and colorectal cancer, however, MIR31HG expression is elevated, serving as an unfavorable prognostic marker and exhibiting oncogenic features." (PMID 37950038, 2024). "Higher expression of MIR31HG can also be found in oral carcinoma, pancreatic ductal adenocarcinoma (PDAC), and nasopharyngeal carcinoma (NPC)." (PMID 37636269, 2023). "LncRNA MIR31HG is upregulated in pancreatic ductal adenocarcinoma and manifests oncogenic properties by influencing cell proliferation and invasiveness." (PMID 29340250, 2018). "While lnc MIR31HG can act as a sponge to bind miR‐193b, miR‐193b can also directly target two binding sites on lnc MIR31HG, negatively regulates lnc MIR31HG levels, induces apoptosis and G1/the S phase arrest, and reduces the cell growth of pancreatic ductal adenocarcinoma." (PMID 38270295, 2024).
colorectal cancer (9 papers, 2015 to 2023). A primary or metastatic malignant neoplasm that affects the colon or rectum. "For example, downregulation of MIR31HG in colorectal cancer was significantly associated with TNM stage, histologic grade, and lymph node metastasis, indicating that MIR31HG expression was linked with poor prognosis in CRC." (PMID 37636269, 2023). "MIR31HG acted as a predictor of survival and risk of recurrence for patients with colorectal cancer." (PMID 36060239, 2022). "For example, eight immune-related lncRNAs (LINC00461, LINC01055, ELFN1-AS1, LMO7-AS1, CYP4A22-AS1, AC079612.1, LINC01351, and MIR31HG) related to the prognosis of patients with colorectal cancer have been identified from TCGA database." (PMID 35144613, 2022). "According to the gene set enrichment analysis (GSEA), MIR31HG may also contribute to colorectal cancer invasion and metastasis by modulating the PI3K-AKT-mTOR-signalling pathway." (PMID 37636269, 2023). "In particular, the lncRNA MIR100HG also acts as a host gene for miRNAs like MIR31HG, and a recent study emphasized its function as a positive regulator in EMT to advance colorectal cancer cell evasion and metastasis." (PMID 37636269, 2023). "Patients with lower MIR31HG appeared to have a worse outcome of OS and DFS in colorectal cancer." (PMID 37636269, 2023).
lung carcinoma (9 papers, 2012 to 2024). "Corroborating this, we found that MIR31HG remarkably regulated both H3K4me and H3K27Ace modification in lung cancer cells." (PMID 37950038, 2024). "Knockdown of GLI2 counteracted MIR31HG-induced cell proliferation, metastasis, and cancer stem cell-mediated multidrug resistance of lung cancer cells." (PMID 37950038, 2024). "Here, we aimed to investigate how MIR31HG influenced lung cancer stem cell-mediated drug resistance, cellular invasion, and stemness features by epigenetically modulating GLI2 expression using mechanistic and functional analyses." (PMID 37950038, 2024). "Our mechanistic investigation revealed that MIR31HG promoted cancer stem cell-related malignant properties of lung cancer cells via H3 histone modification of GLI2 transcriptional activity and its downstream stemness-related molecules." (PMID 37950038, 2024). "In the present study, we showed that GLI2 can be epigenetically upregulated at the transcriptional level by MIR31HG, exerting lung cancer cell stemness-related multidrug resistance, and cellular invasion." (PMID 37950038, 2024). "LINC00942, LINC01116, SNHG4, MIR31HG, and LINC00460 had been known to be associated with tumor development and progression and drug resistance in various cancers including lung cancer." (PMID 35083132, 2021). "Overexpression of MIR31HG suggested remarkable association with poor prognosis in terms of OS, tumor stage, and LNM in lung cancer, but favorable prognosis in gastrointestinal cancer." (PMID 32280307, 2020). "Taken together, our study provided evidence that MIR31HG overexpression suggested remarkable association with poor prognosis in terms of OS, tumor stage, and LNM in lung cancer, but favorable prognosis in gastrointestinal cancer." (PMID 32280307, 2020). "Moreover, the spheroid formation assay showed that exogenous MIR31HG stimulated lung cancer stem cell proliferation and knockdown prevent cell expansion." (PMID 37950038, 2024). "Since our previous study demonstrated that the Hedgehog cascade is related to lung cancer stemness features and multidrug resistance, we focused on whether MIR31HG functions via the Hedgehog pathway." (PMID 37950038, 2024). "Additionally, MIR31HG overexpression was significantly associated with worse clinicopathological features including advanced tumor stage and LNM in lung cancer, but favorable clinical characteristics in gastrointestinal cancer." (PMID 32280307, 2020). "Notably, MIR31HG overexpression predicted unfavorable OS in lung cancer." (PMID 32280307, 2020). "To determine whether MIR31HG functions through GLI2, we first investigated the function of GLI2 regarding lung cancer stemness-related cellular proliferative advantage and drug resistance." (PMID 37950038, 2024). "Similarly, KRT6A, MIR31HG, and FOLR1 have been found to enhance lung cancer proliferation and may be potential therapeutic targets." (PMID 38926418, 2024). "Moreover, MIR31HG was more highly expressed in stage IV lung cancer than in stages I-III, though the difference was not significant." (PMID 37950038, 2024).
bladder cancer (8 papers, 2017 to 2024). "Growing evidence shows that MIR31HG expression is suppressed in bladder cancer and was consistent with the pan-cancer analysis." (PMID 37636269, 2023). "In vitro experiments revealed that knockdown of MIR31HG inhibits cell proliferation, colony formation, and migration in bladder cancer." (PMID 33334367, 2020). "In this study, a decreased expression of MIR31HG was found in bladder cancer cells and tissues, except in the basal subtype." (PMID 33334367, 2020). "Furthermore, MIR31HG expression was analyzed in RNA-seq data from the Cancer Cell Line Encyclopedia containing 25 BLCA cell lines, including 20 bladder urothelial cell carcinomas, a bladder squamous cell carcinoma, and four bladder carcinoma cell lines from unknown primaries." (PMID 33334367, 2020).
oral cancer (8 papers, 2017 to 2024). "Also, MIR31HG expression has been investigated and found increased in HNSCCs and oral cancers, where it has been reported as a lncRNA induced by HIF-1α." (PMID 35456025, 2022). "Moreover, in oral cancer, MIR31HG directly binds with HIF-1α and forms a special complex." (PMID 37636269, 2023). "MIR31HG then interacts with HIF-1α itself, favoring its recruitment on target promoters involved in oral cancer progression." (PMID 35456025, 2022). "In contrast, MIR31HG acts as an HIF-1α co-activator and drives oral cancer progression." (PMID 35743003, 2022). "In addition, MIR31HG could recruit HIF-1α and its cofactors to targets genes and activate the HIF-1 transcriptional network in oral carcinoma." (PMID 37950038, 2024).
psoriasis (7 papers, 2018 to 2024). An autoimmune condition characterized by red, well-delineated plaques with silvery scales that are usually on the extensor surfaces and scalp. "LncRNA‐MSX2P1, MIR31HG, and lncRNA‐H19 are up‐regulated in psoriasis lesions, which can affect the proliferation and apoptosis of keratinocytes and induce the production of inflammatory factors." (PMID 38174774, 2024). "Recently, more evidence has also shown that MIR31HG also participates in other diseases in addition to cancer, such as psoriasis, IgA nephropathy (IgAN), hirschsprung’s disease, rheumatoid arthritis (RA), and osteonecrosis of the femoral head (ONFH)." (PMID 37636269, 2023). "Other upregulated lncRNA in psoriasis are MIR31HG, MSX2P1, XIST, FABP5P3, KLDHC7B-DT, or SPRR2C; whereas, MEG3, GAS5, PRINS or NEAT1 are downregulated in psoriasis." (PMID 37628670, 2023). "For instance, lncRNA H19 and MIR31HG play an essential role in keratinocyte differentiation, indicating the potential function of H19 and MIR31HG in pathogenesis of psoriasis." (PMID 34080300, 2021). "In the present study, we aimed to investigate the expression of MIR31HG in psoriasis lesions and normal skins and determine the effects of MIR31HG knockdown on the proliferation of human HaCaT keratinocytes." (PMID 30180891, 2018). "Our findings provide evidence that MIR31HG plays an important role in regulation of keratinocytes hyperproliferation in psoriasis and may be an attractive therapeutic target." (PMID 30180891, 2018). "In psoriasis, MIR31HG was found to be elevated in psoriasis lesions and the upregulation of MIR31HG required IL-17A, IL-22, TNF-α, and IL-1α stimulation, demonstrating that nuclear factor kappa B inhibitor (NF-κB) signalling could be crucial crosstalk in psoriasis." (PMID 37636269, 2023). "LncRNAs have been revealed to participate in the pathogenesis of psoriasis, including MEG3, GAS5, and MIR31HG." (PMID 35586566, 2022). "While a number of lncRNAs such as MEG3, AL162231.4 and NONHSAT044111 have been down-regulated in the course of psoriasis, others including PRINS, MIR31HG, RP6‐65G23.1, MSX2P1, SLC6A14-1:1, NR_003062 have been up-regulated." (PMID 32695942, 2020). "In addition to human cancer, in specific human non-cancer MIR31HG overexpression was able to be found in psoriasis, IgAN, RA, and ONFH." (PMID 37636269, 2023). "However, the function of MIR31HG in psoriasis has not been investigated." (PMID 30180891, 2018).
hepatocellular carcinoma (5 papers, 2020 to 2024). A malignant tumor that arises from hepatocytes. "MIR31HG play a role of tumor suppressor in hepatocellular carcinoma by acting as a ceRNA to downregulate the oncogenic microRNA-575." (PMID 37950038, 2024). "Controversially, MIR31HG is downregulated in bladder cancer, esophageal squamous cell carcinoma, and hepatocellular carcinoma." (PMID 35743003, 2022). "For example, MIR31HG inhibits cell proliferation and metastasis in hepatocellular carcinoma." (PMID 35743003, 2022). "In addition, MIR31HG inhibited hepatocellular carcinoma (HCC) proliferation and metastasis by directly binding miR-575 to positively modulate the expression of ST7L." (PMID 37636269, 2023).
lung adenocarcinoma (5 papers, 2022 to 2025). A carcinoma that arises from the lung and is characterized by the presence of malignant glandular epithelial cells. "MIR31HG was aberrantly overexpressed in both lung adenocarcinoma (LUAD) and lung squamous cell carcinoma (LUSC) tumor tissues compared to levels in normal specimens based on data from the GEPIA database." (PMID 37950038, 2024). "According to the latest research from Mo’s team, MIR31HG serves as an oncogene by targeting mir-193a-3p and positively enhances recombinant tumor necrosis factor receptor superfamily, member 21 (TNFRSF21) expression in lung adenocarcinoma." (PMID 37636269, 2023).
melanoma (5 papers, 2017 to 2023). A malignant, usually aggressive tumor composed of atypical, neoplastic melanocytes. "Knockdown of MIR31HG induces melanoma cell senescence, which is associated with re-expression of p16INK4A." (PMID 37325482, 2023). "The expression of MIR31HG is significantly upregulated in melanoma tissues and cell lines, compared with their normal counterparts, and this upregulation is positively correlated with lymph node metastasis, distal metastasis, and TNM stage." (PMID 37325482, 2023). "One study demonstrated that the expression of MIR31HG was significantly upregulated in melanoma." (PMID 37636269, 2023). "miR-31 host gene (MIR31HG) lncRNA is upregulated in OIS upon BRAF overexpression, binds directly to SUZ12 polycomb repressive complex 2 subunit and EZH2, thus is required for the repression of the INK4A locus, whereas knockdown of MIR31HG promotes a p16INK4A-dependent senescence of melanoma cells." (PMID 34638331, 2021). "MIR31HG and ANRIL are two lncRNAs that regulate this genomic locus through interactions with PRC1 and PRC2 in melanoma." (PMID 34638331, 2021). "Several studies have identified known lncRNAs that are abnormally expressed in melanoma, such as SAMMSON, HOTAIR, SLNCR1, BANCR, SPRY4-IT1, ANRIL, Llme23, UCA1, MALATA1, GAS5, H19, CASC15, PTENP1, and MIR31HG." (PMID 28225791, 2017).
head and neck squamous cell carcinoma (4 papers, 2020 to 2023). A squamous cell carcinoma that arises from any of the following anatomic sites: lip and oral cavity, nasal cavity, paranasal sinuses, pharynx, larynx, and salivary glands. "In GEPIA, with RP11-54H7.4, MIR31HG, LINC00152, and LINC00511 being upregulated and H19, CTD-2545M3.8, RP11-760H22.2, and RP4-791M13.3 being consistently downregulated in head and neck squamous cell carcinoma (HNSC)." (PMID 32923393, 2020).
non-small cell lung carcinoma (3 papers, 2021 to 2023). A group of at least three distinct histological types of lung cancer, including non-small cell squamous cell carcinoma, adenocarcinoma, and large cell carcinoma. "In addition, previous studies in non-small cell lung cancer and osteosarcoma cells also identified a promoting role of MIR31HG in the EMT." (PMID 35743003, 2022). "For example, in non-small cell lung cancer (NSCLC), MIR31HG functions as an independent predictor of poor overall survival (OS) of NSCLC patients, and also promotes tumor progression." (PMID 34485123, 2021).
osteosarcoma (3 papers, 2020 to 2022). A usually aggressive malignant bone-forming mesenchymal neoplasm, predominantly affecting adolescents and young adults. "MIR31HG acts as an oncogene in osteosarcoma to promote tumor progression via regulation of tumor suppressor miR-361 and its target genes." (PMID 36057712, 2022). "MIR31HG was up-regulated in osteosarcoma (OS) tissues and OS cell lines." (PMID 36057712, 2022).